SHBG (sex hormone binding globulin)
Diseases named in the same sentence as SHBG in open-access papers (continued):
Sharing a sentence is not in itself a finding about the gene and the disease.
Stroke (continued). "In addition, SHBG accounted for 18.4% of the total effect of TG on small-vessel stroke, whereas the mediating effects of SHBG on the associations between T2DM and SBP with stroke risk were too low to be noteworthy." (PMID 40728963, 2025). "Although marginal heterogeneities were observed in some cardiometabolic traits (e.g., WC, WHR, SBP, and DBP) with SHBG or stroke, both of the IVW-mre and “leave-one-out” analyses found that the causal estimates were not influenced by any one instrumental variable of SNP." (PMID 40728963, 2025). "The MR results indicated a protective effect of genetically increased SHBG levels on any stroke (odd ratio [OR] = 0.941; 95% confidence interval [CI]: 0.898, 0.984), any ischemic stroke (OR = 0.951; 95% CI: 0.922, 0.981), and small-vessel stroke (OR = 0.871; 95% CI: 0.765, 0.977)." (PMID 40728963, 2025). "These pathways support SHBG as a potential biomarker and therapeutic target in stroke prevention." (PMID 40728963, 2025). "Furthermore, genetically determined SHBG levels mediated the greater effects on the associations between WC and WHR with any stroke, any ischemic stroke, and small-vessel stroke, and the mediating ratios ranged from 33.5 to 68.3%." (PMID 40728963, 2025). "In our bi-directional and multivariable MR study, an inverse causal association between SHBG and stroke (and IS) is observed, indicating that SHBG may play a protective effect on stroke and IS." (PMID 38596080, 2024). "Evidence regarding the role of SHBG in the pathogenesis of stroke are limited." (PMID 38596080, 2024). "Third, we merely used summary-level data in our MR analyses because of the limited publicly available individual-level data; therefore, the possibility of a non-linear causal relationship or interaction association between SHBG levels and risk of stroke or cardiometabolic traits cannot be ruled out." (PMID 40728963, 2025). "The level of SHBG may be influenced by multiple factors after stroke." (PMID 38596080, 2024). "In the reverse MR analysis, no causal effects of stroke and its subtypes on SHBG." (PMID 38596080, 2024). "Additionally, we confirm the direction of the causal effect of SHBG on stroke, while not the opposite." (PMID 38596080, 2024). "Our results demonstrated that the effect of IVs on stroke, IS and SVS are reduced with the growth of SNPs’ effects on SHBG." (PMID 38596080, 2024). "For the mediator models based on the categorical weight change variable, we identified age, smoking, alcohol use, walking, COPD, stroke, estrogen use, IGF-1, 25(OH)D, albumin, height, ln-SHBG, and ln-PTH as confounders." (PMID 34272641, 2022). "In the analyses of subtypes, protective effects of SHBG on stroke are not detected, indicating the heterogeneity of different subtypes." (PMID 38596080, 2024). "Lastly, we could not conduct sex-stratified analysis of SHBG levels and stroke due to data unavailability." (PMID 40728963, 2025). "Additionally, we did not explore the role of SHBG on stroke in sex stratification due to unavailability of male and female stroke dataset." (PMID 38596080, 2024). "Furthermore, no obvious causal effects of stroke, IS, LAS, and CES on SHBG are detected." (PMID 38596080, 2024).
amenorrhea (5 papers, 2018 to 2025). The absence of menses in a woman who has achieved reproductive age. "This study highlights the relationship between MetS, its components, and important biomarkers and clinical indicators of PCOS including TT, SHBG, amenorrhea, and OCP use." (PMID 40308359, 2025). "In general, participants with MetS were older, had a higher BMI, lower mean TT and SHBG concentrations, and a higher prevalence of amenorrhea and OCP usage compared to those without MetS." (PMID 40308359, 2025). "Consequently, we relied on surrogate biomarkers of PCOS such as TT, SHBG concentrations, and amenorrhea, which may not capture the true prevalence of the condition." (PMID 40308359, 2025).
benign prostatic hyperplasia (5 papers, 2013 to 2024). A non-cancerous nodular enlargement of the prostate gland. "The roots of the Eurasian plant U. dioica L., popularly known as stinging nettle, has been used to treat benign prostatic hyperplasia, for their anti-inflammatory effects and binding inhibition of sex hormone binding globulin (SHBG) to its receptor in prostate cells." (PMID 33918334, 2021). "From the results of our cohort study, we believe that the plasma testosterone level, or SHBG level may not affect the development of prostatic hyperplasia because plasma levels of androgens may not accurately reflect their concentrations within the prostate gland." (PMID 39582249, 2024).
chronic kidney disease (5 papers, 2022 to 2025). Impairment of the renal function secondary to chronic kidney damage persisting for three or more months. "A mendelian randomization study from the United Kingdom Biobank population suggested that high sex hormone-binding globulin was associated with better kidney function and a lower risk of chronic kidney disease (CKD) in men." (PMID 37821826, 2023). "Interestingly, chronic kidney disease (CKD) is a factor responsible for decreasing testosterone levels, depending on the CKD stage, whereas SHBG remains consistent." (PMID 40427034, 2025). "Furthermore, neither kidney transplantation nor worsening kidney function in chronic kidney disease had been shown to influence SHBG levels." (PMID 39014506, 2024).
dyslipidaemia (5 papers, 2016 to 2025). "Hepatic resistance to TH action manifests as normal, circulating sex hormone binding globulin (SHBG) and mixed dyslipidaemia." (PMID 35999191, 2022).
Dysmenorrhea (5 papers, 2022 to 2025). Pain during menstruation that interferes with daily activities. "Smoking causes short menstrual cycles, dysmenorrhea, early menopause, and adverse effects on folliculogenesis, lowers blood and follicular fluid progesterone and estrogen levels, and increases serum testosterone and sex-hormone-binding globulin (SHBG) levels, thus affecting reproductive function." (PMID 36548560, 2022). "In an earlier published study with a cross-over design conducted in women with dysmenorrhea, a low-fat vegetarian diet increased sex hormone binding globulin (SHBG) levels and reduced pain." (PMID 37834048, 2023). "In this study, preoperative, 3rd-month, and 6th-month measurements of weight, BMI, FSH, LH, total testosterone, AMH, DHEA-S, SHBG, and androstenedione and dysmenorrhea were evaluated using the Kolmogorov–Smirnov test, which indicated that these variables were not normally distributed (p < 0.05)." (PMID 40555929, 2025). "However, no causal effects were found between alcohol drinking and SHBG, bio-T, E2, and AMH levels (respectively), as well as irregular menstrual cycle/bleeding and dysmenorrhea (respectively), even after the heterogeneity and horizontal pleiotropy were eliminated." (PMID 37091804, 2023).
gout (5 papers, 2020 to 2026). A condition characterized by painful swelling of the joints, which is caused by deposition of urate crystals. "Higher SHBG levels were associated with a lower risk of gout (0.92 [0.90–0.93], p < 10-6) in the EUR ancestry group." (PMID 40316537, 2025). "Another beneficial effect of high SHBG was observed on gout, and this association appeared to be predominant in males (more cases) even though a suggestive inverse association was observed in females as well (not shown)." (PMID 35218343, 2022). "Our two-sample MR study further observed an inverse association between uric acid and genetically predicted SHBG, which supports the novel findings on sex disparity of gout prevalence." (PMID 35218343, 2022). "A Mendelian randomization study showed that higher testosterone levels based on genetic prediction in males were associated with a lower risk of type 2 diabetes, gout, and celiac disease while noting that sex hormones, sex hormone-binding globulin, and metabolic diseases are strongly associated." (PMID 38751428, 2024). "In females, we found that UA level was negatively associated with TT, E2, SHBG, CDAI, VitC, and Zinc, while the SHAP summary plot showed that elevated SII increased the risk of gout." (PMID 38751428, 2024). "Two-sample Mendelian randomization (MR) analysis assessed the causality between sex hormones (total testosterone [ToT], bioavailable testosterone [BioT], SHBG, estradiol, age at menarche, and age at menopause) and serum urate or gout, followed by sex-stratified analysis." (PMID 42016019, 2026). "Our study found a negative correlation between UA level and TT, SHBG, CDAI, VitA, and VitC in males, and the SHAP summary plot suggests that elevated SII and decreased DA intake also increase the risk of gout." (PMID 38751428, 2024).
hyperuricemia (5 papers, 2017 to 2024). An abnormally high level of uric acid. "Changes in hormones in patients with hyperuricaemia may also be associated with changes in their plasma SHBG levels." (PMID 33906696, 2021). "Lower SHBG concentrations are predictive of hyperuricemia, suggesting a potential link between SUA and SHBG production via AMPK inactivation in the liver." (PMID 39006368, 2024). "Hyperuricemia can reduce the level of insulin-like growth factors binding to protein 3 and reduce the level of SHBG." (PMID 29109738, 2017).
Impaired glucose tolerance (5 papers, 2018 to 2023). An abnormal resistance to glucose, i.e., a reduction in the ability to maintain glucose levels in the blood stream within normal limits following oral or intravenous administration of glucose. "There is a wide range of risk factors that lead to the development of GDM in the setting of PCOS, and while there is overlap with the development of GDM in healthy controls, low SHBG preconception was found to be a significant risk factor, along with BMI and preconception impaired glucose tolerance." (PMID 38234933, 2023). "For example, it has been shown that post-menopausal women aged 57–59 years with impaired glucose tolerance have higher androgen activity, i.e., lower sex hormone-binding globulin (SHBG) levels and higher testosterone-to-SHBG ratios than normal, glucose-tolerant post-menopausal women." (PMID 38068890, 2023).
invasive breast carcinoma (5 papers, 2011 to 2023). A carcinoma that infiltrates the breast parenchyma. "Overall, the findings from this large prospective cohort study confirm significant associations of testosterone, IGF-1 and SHBG with the risk of invasive breast cancer, with evidence of heterogeneity by menopausal status for testosterone." (PMID 33864017, 2021). "In this study, involving about 160,000 women, there were significant associations of testosterone, IGF-1 and SHBG with the risk of invasive breast cancer, with evidence of heterogeneity observed by menopausal status for testosterone." (PMID 33864017, 2021). "We, therefore, investigated the associations between serum concentrations of testosterone, sex hormone-binding globulin (SHBG) and IGF-1 and the risk of invasive breast cancer in pre- and post-menopausal women in UK Biobank." (PMID 33864017, 2021). "Among the 11 hematological and biochemical biomarkers found to be associated with the risk of invasive breast cancer, some were inflammatory markers, such as white blood cell count, neutrophil count, and CRP, while others were endogenous hormones, such as SHBG, IGF-1, and testosterone." (PMID 38000092, 2023). "In this context, we analyzed changes in estradiol, progesterone, testosterone, FSH, LH, dehydroepiandrosterone sulfate (DHEAS), sex hormone-binding globulin (SHBG) levels, and free androgen index (FAI) after NAC treatment in pre- and postmenopausal women diagnosed with invasive breast cancer." (PMID 36117838, 2022). "The results were similar for invasive breast cancer and when using free estradiol and free testosterone instead of total levels, although the sample size was decreased because of missing SHBG levels (data not shown)." (PMID 22017816, 2011).
ischemic stroke (5 papers, 2018 to 2025). A stroke disorder caused by obstruction of blood flow to the brain, due to thrombotic (local blood clot formation) or embolic (due to a blood clot or other material traveling from another site) event. "A prospective study of 13,192 women in the United States who had gone through menopause showed a significant inverse association between serum SHBG levels and the incidence of ischemic stroke, even after adjusting for T2DM, estradiol and testosterone levels." (PMID 40728963, 2025). "One previous study from the Women's Health Initiative supported an inverse association between serum SHBG levels and ischemic stroke (IS) risk." (PMID 38596080, 2024). "Consistent with the results of a prospective cohort study in postmenopausal women, a protective effect of genetically determined SHBG levels on ischemic stroke was detected in the present study, particularly for the etiologic subtype of small-vessel stroke." (PMID 40728963, 2025).
liver dysfunction (5 papers, 2021 to 2025). "In these patients, a certain grade of hypothalamic–pituitary dysfunction is plausible, so that there is an inadequate response to liver dysfunction and increased SHBG levels." (PMID 33515211, 2021). "At the same time, alcohol-related liver dysfunction may elevate sex hormone-binding globulin, thereby reducing bioavailable testosterone." (PMID 40978927, 2025). "Given that SHBG is synthesized in the liver and transports sex hormones in serum, liver dysfunction may lead to decreased SHBG." (PMID 37752940, 2023). "The role of SHBG as a marker of metabolic alterations is not fully understood; indeed, it can be a cause or a consequence of liver dysfunction." (PMID 36421197, 2022).
thyrotoxicosis (5 papers, 2016 to 2025). A hypermetabolic syndrome caused by the elevation of thyroid hormone levels in the serum. "Underlying mechanisms for the association with thyrotoxicosis could involve oxidative stress or increased production of sex hormone-binding globulin." (PMID 29049401, 2017). "Thyrotoxicosis results in increased serum levels of sex hormone binding globulin (SHBG) due to increase in estradiol levels, and a reduction of the metabolic clearance rate of estradiol." (PMID 35945393, 2023). "On the other hand, men with thyrotoxicosis show an increase in SHBG and total testosterone, with normal free testosterone, reduced testosterone clearance rate and free testosterone/estradiol rate, due to elevated total and free estradiol concentration." (PMID 35945393, 2023). "SHBG is increased in thyrotoxicosis patients as a result of hepatic stimulation by thyroid hormones." (PMID 28044109, 2016). "Severe thyrotoxicosis can increase SHBG levels and slightly decrease albumin levels." (PMID 39901894, 2025).
type 1 diabetes (5 papers, 2018 to 2025). "Uric acid and insulin-like growth factor-1 (IGF-1) were lower, and sex hormone binding globulin (SHBG) was higher, in participants with type 1 diabetes." (PMID 41285865, 2025). "Women with type 1 diabetes combined with PCOS may have normal or elevated levels of SHBG and lower concentrations of free androgens." (PMID 37957681, 2023). "These latter results are, however, at odds with the normal SHBG levels in patients with type 1 diabetes who are also hyperglycemic, and with studies in patients with T2DM treated with rosiglitazone whose SHBG levels increased." (PMID 40863113, 2025).
acromegaly (4 papers, 2019 to 2024). Acromegaly is an acquired disorder related to excessive production of growth hormone (GH) and characterized by progressive somatic disfigurement (mainly involving the face and extremities) and systemic manifestations. "Based on this premise, a Consensus of experts recommends measurement of total testosterone, Sex-Hormone Binding Globulin (SHBG) and prolactin for the evaluation of gonadal function in men with acromegaly at diagnosis and then annually." (PMID 35364803, 2022). "Although androgen levels are not generally increased in women with acromegaly, the circulating levels of sex hormone binding globulin (SHBG) were found to be low in a retrospective analysis." (PMID 31417493, 2019).
alcohol dependence (4 papers, 2024 to 2025). Physical and psychological dependence on alcohol. "Levels of BMI-adjusted SHBG were positively associated with alcohol dependence in both sexes, although the genetic correlation was null in females." (PMID 40766921, 2025). "Recently we described associations of alcohol consumption and alcohol dependence with testosterone, estradiol, SHBG, and albumin in data from the UK Biobank, with striking differences by sex14." (PMID 38464231, 2024). "Additionally, alcohol dependence was positively associated with BMI-adjusted levels of SHBG and similarly trended toward positive genetic correlation with BMI-adjusted SHBG in males." (PMID 40766921, 2025). "Additionally, alcohol dependence was positively associated with BMI-adjusted levels of SHBG and was also positively genetically correlated with BMI-adjusted SHBG in males." (PMID 38464231, 2024). "In this study, we observed major differences in the genetic correlation of SHBG with both alcohol consumption and alcohol dependence that depended on adjustment for BMI in the GWAS of SHBG." (PMID 40766921, 2025). "Using UK Biobank data, we observed higher total testosterone and SHBG levels, but lower albumin levels, in both males and females with alcohol dependence history." (PMID 40766921, 2025). "SHBG also trended toward positive genetic correlation with alcohol dependence in males, but only after adjustment for BMI in the GWAS of SHBG." (PMID 38464231, 2024). "Shared genetic effects may contribute to the positive relationship between alcohol consumption and levels of albumin in both sexes, and between alcohol dependence and levels of BMI-adjusted SHBG in males." (PMID 40766921, 2025). "Importantly, these alcohol dependence-related endocrine fluctuations are also ascribed to the variations in sex hormone-binding globulin (SHBG) production, the main hepatic protein regulating sex hormones’ bioavailability." (PMID 39590862, 2024). "Levels of BMI-adjusted SHBG were positively associated with alcohol dependence in both sexes, but there was no genetic correlation in females unlike males." (PMID 38464231, 2024). "Findings suggest that shared genetic effects may contribute to positive associations of alcohol consumption with albumin in both sexes, as well as positive associations between alcohol consumption and bioavailable testosterone and between alcohol dependence and SHBG in males." (PMID 38464231, 2024). "We also found that alcohol dependence trended toward negative genetic correlation with total testosterone in females and also trended toward positive genetic correlation with SHBG in males, but only when the GWAS of SHBG was adjusted for BMI." (PMID 40766921, 2025). "For alcohol dependence, we observed trends toward negative genetic correlation with total testosterone in females (rg = -0.106, p = 0.024) and positive genetic correlation with BMI-adjusted SHBG in males (rg = 0.119, p = 0.017)." (PMID 40766921, 2025). "There was no genetic correlation of alcohol dependence with SHBG in females (rg = -0.02, p = 0.70) or males (rg = 0.07, p = 0.18); however, alcohol dependence trended toward positive genetic correlation with BMI-adjusted SHBG in males (rg = 0.12, p = 0.02) but not females (rg = 0.03, p = 0.61)." (PMID 40766921, 2025). "Overall, no significant genetic correlations were observed for alcohol dependence; however, there were trends towards negative genetic correlation with total testosterone in females and positive genetic correlation with BMI-adjusted SHBG in males." (PMID 40766921, 2025). "For alcohol dependence, we observed a trend toward negative genetic correlation with total testosterone in females (rg = −0.106, p = 0.024) and positive genetic correlation with BMI-adjusted SHBG in males (rg = 0.119, p = 0.017)." (PMID 38464231, 2024).